AXL (AXL receptor tyrosine kinase)
Diseases named in the same sentence as AXL in open-access papers (continued):
Sharing a sentence is not in itself a finding about the gene and the disease.
cancer (continued). "Thus, AXL can potentially serve as a diagnostic and prognostic biomarker for various cancers." (PMID 34442532, 2021). "Thus, AXL associated with the development of EMT may be a promising therapeutic target for the elimination of cancer in ALK-positive NSCLC cells." (PMID 29930762, 2018). "AXL was identified as one of the most highly expressed genes following DV treatment (18-fold induction) and was of particular importance as it is implicated in many cancers A number of its oncogenic properties include a role in cell proliferation, survival and inhibition of apoptosis." (PMID 28881658, 2017). "As we have demonstrated that the abundance of AXL-FL is largely dependent on shedding and intramembrane cleavage by α- or γ- secretases in several types of cancers, it may suggest that reduced proteolytic activities could universally cause the accumulation of AXL-FL in cell membranes." (PMID 28034848, 2017). "Previous BrM protein profiling revealed that AXL, a member of the TAM (TYRO3, AXL, MER) receptor tyrosine kinase family implicated in oncogenesis and metastasis of many cancer types is elevated in BrM cells." (PMID 41356185, 2026). "AXL is a receptor tyrosine kinase with a significantrole in variousbiological processes and important medical implications, particularlyin cancer." (PMID 41552498, 2026). "AXL is overexpressed in several cancers, like lung, liver, renal, pancreatic, and ovarian cancers, especially in TNBC tumors, where it is associated with poor clinical outcomes." (PMID 41009462, 2025). "Upon co-incubation with AXL-positive cancer cells, the mfhAXL CAR-T cells were specifically activated to secrete IL-2 and IFN-γ, indicating their selective responsiveness to the antigen." (PMID 40299452, 2025). "After activation, downstream signaling pathways like PI3K/AKT, MAPK, and JAK/STAT are stimulated by AXL autophosphorylation, which in turn regulates the functions of cancer cells." (PMID 39755633, 2025). "Western blot and immunofluorescence assays demonstrated that all tested cancer cells expressed AXL, with high levels observed in TE-1, KYSE30, and A2780 cells and relatively low levels in MKN45 cells." (PMID 40157901, 2025). "Recent studies have identified various mechanisms through which AXL interacts with other RTKs, to promote cancer cell survival, proliferation, invasiveness, and drug resistance." (PMID 39924521, 2025). "In order to enhance the reliability of our conclusion regarding the STAMBPL1 KD‐mediated destabilization of AXL, primary cancer cells were isolated from KIRC tissues." (PMID 39527690, 2025). "In many cancers, AXL is overexpressed and aids in the proliferation, invasiveness, and migration of tumor cells." (PMID 39395205, 2025). "AXL, a receptor tyrosine kinase, has recently emerged as a potential therapeutic target against various types of cancer." (PMID 40157901, 2025). "Although these studies provide a foundation, further research across different cancer types is needed to determine the precise molecular mechanisms through which AXL alters glucose metabolism to induce drug resistance." (PMID 39924521, 2025). "AXL mRNA was also significantly higher in Cisplatin-resistant cancer cells than in Cisplatin-sensitive cancer cells ​." (PMID 40813689, 2025). "We collected and analysed RNA data from normal (n = 32) and cancer patients groups (n = 375) in the TCGA database to investigate AXL expression in pan-cancer." (PMID 39644434, 2025). "Given that metastasis accounts for approximately 90% of cancer-related deaths, targeting AXL-driven migration and invasion is a critical therapeutic objective." (PMID 41009462, 2025). "Given that AXL plays a crucial role in cancer progression and therapeutic resistance, combining AXL inhibitors with other receptor tyrosine kinase inhibitors offers a promising strategy for overcoming acquired resistance and enhancing drug sensitivity." (PMID 39924521, 2025).
cancer (continued). "AXL is a key driver of stemness in cancer cells, facilitating self-renewal and contributing to the long-term maintenance of tumors." (PMID 39924521, 2025). "This variation, including a 100-fold difference in plasma membrane AXL concentration between chemo-sensitive and chemoresistance cells, highlights the importance of selecting appropriate cancer models for therapeutic screening." (PMID 39924521, 2025). "TAM receptors, including AXL, are crucial not only for cancer cell proliferation and survival but also for vessel integrity and angiogenesis." (PMID 39924521, 2025). "Compared to the control cells, the protein half‐life of endogenous AXL was dramatically decreased and the ubiquitination of AXL was significantly increased in shSTAMBPL1 treated primary cancer cells." (PMID 39527690, 2025). "Considering AXL’s pivotal role in cancer initiation, progression, metastasis and therapeutic resistance, future research holds promise in uncovering the translational potential of AXL as a biomarker for predicting treatment responses." (PMID 39924521, 2025). "Mechanistically, we found that STAMBPL1 positively modulated mesenchymal and immune evasion phenotypes of cancer cells largely through removing ubiquitination on AXL, one member of TAM receptors." (PMID 39527690, 2025). "Treatment with pacDNA in AXL‐overexpressing cell lines significantly inhibits AXL phosphorylation, resulting in reduced cancer cell migration and invasion." (PMID 40566927, 2025). "Overall, the crosstalk between AXL with other RTKs contributes to resistance against both conventional and targeted therapies across diverse cancers." (PMID 39924521, 2025). "Collectively, these findings revealed gilteritinib as a potent therapeutic agent for treating AXL-positive cancers." (PMID 40157901, 2025). "Given its role in cancer development, AXL has emerged as a promising prognostic marker and therapeutic target." (PMID 41004176, 2025). "Targeting AXL receptor kinase with a highly selective antibody presents a promising approach for inhibiting AXL and potentially improving cancer treatment." (PMID 41004176, 2025). "Subsequently, we analysed the expression levels of these genes across 33 types of cancer and found that AXL, MERTK, TYRO3, CD24, HAVCR2 and CD47 exhibited higher expression levels, while TIMD4 and HAVCR1 showed relatively lower expression." (PMID 40576208, 2025). "A novel cancer immunotherapy, anti-AXL chimeric antigen receptor (CAR)-T-cell therapy, has shown promise as a potential treatment option." (PMID 39924521, 2025). "To further elucidate the impact of the STAMBPL1/TRIM21/AXL axis on metastasis in vivo, we constructed the tail‐vein cancer metastasis model using 786‐O sublines in BALB/c nude mice." (PMID 39527690, 2025). "Cabozantinib, a multikinase inhibitor targeting VEGFR2, c-MET, RET, and AXL, has shown efficacy in overcoming resistance to other therapies across various cancers." (PMID 39924521, 2025). "We utilized the A549 and Panc-1 cancer cells, both of which are characterized by high AXL expression, as target cells for the mfhAXL CAR-T cells." (PMID 40299452, 2025). "Conversely, in Lassa and Ebola viruses, the entry through AXL depends on AXL kinase activity and via macropinocytosis, which is also utilized in cancer cells for AXL-dependent invasion (16, 28, 53, –, 56)." (PMID 40853130, 2025). "The association between tAXL expression and poor ECOG-performance status, larger tumors, and inflammation suggests that AXL-signaling elicits an aggressive cancer phenotype." (PMID 39238637, 2024). "Although AXL+ cells are in general considered to be cancer cells, our analysis clearly revealed that AXL expression is highest in CAFs and TAMs." (PMID 39697983, 2024). "AXL is activated in many cancers, with an important role in cell proliferation, motility, and the promotion of an immunosuppressive local microenvironment." (PMID 38369783, 2024).
cancer (continued). "AXL was sequentially cleaved by α- and γ-secretases in cancer cells, which generated an intracellular domain termed as AXL–ICD that translocated to the nucleus." (PMID 39062902, 2024). "AXL is involved in many crucial roles in cancer development, including cell movement, immunosuppression, and epithelial–mesenchymal transitions (EMTs)." (PMID 38732242, 2024). "While AXL expression on cancer cells is readily recognized, it is less well known that AXL is expressed by a variety of host cells found in the TME, including several immune cell types, fibroblasts, osteoclasts, and endothelial cells." (PMID 38546390, 2024). "It is important to emphasize that AXL is not only expressed by malignant cancer cells, but can also be located on the surface of various other cells, including immune cells." (PMID 38773967, 2024). "Next, we evaluated the cell binding potential of sdAbs to AXL+ cancer cells (human HCT-116, murine CT26) using flow cytometry and sdAb affinity was determined using surface plasmon resonance." (PMID 38773967, 2024). "Since AXL is detectable in approximately 50% of the AML patients and appears to be highly predictive for response to AXL-targeted therapies (like bemcentinib) 6, monitoring AXL expression in cancer patients is highly recommended." (PMID 38773967, 2024). "AXL's pleiotropic role in cell survival, drug resistance and immune suppression makes it a promising target for cancer therapy." (PMID 38773967, 2024). "In this study, we developed AXL-specific single domain antibodies (sdAbs), cross-reactive for both mouse and human AXL protein, to non-invasively image and treat AXL-expressing cancer cells." (PMID 38773967, 2024). "AXL overexpression is commonly observed in several types of cancer, including breast, lung, ovarian, and renal cell carcinomas." (PMID 39597836, 2024). "Our study demonstrates the novel function of C-mannosylation through the effect of AXL functions and provides the possibility that C-mannosylation of AXL becomes the therapeutic target of cancers." (PMID 39660536, 2024). "AXL inhibition in cancer has been shown to induce cell apoptosis and DNA damage, decrease cell proliferation and migration, and improve sensitivity to chemotherapeutic drugs." (PMID 39598377, 2024). "Previous studies have also revealed a critical role of AXL in contributing to drug resistance towards various anti-cancer therapies such as chemotherapy and targeted therapy." (PMID 38310091, 2024). "GAS6 upregulation or AXL overexpression is often found in cancers with resistance to EGFR-targeted therapy and enhanced survival." (PMID 38892166, 2024). "The advantages of using AXL inhibitors goes further since it has been recently shown that AXL inhibitors enhance chemosensitivity for cisplatin in different cancer types, likely by reducing drug resistance." (PMID 38501485, 2024). "The therapeutic targeting of AXL has gained significant attention due to its prevalent overexpression in numerous cancer cells, as well as its involvement in the polarization of macrophages towards the M2-like phenotype." (PMID 39346737, 2024). "In this context, the receptor tyrosine kinase (RTK) AXL is an attractive target molecule whose expression is essential for maintaining mesenchymal phenotype in different cancers, including TNBC12–14." (PMID 38172210, 2024). "AXL was shown to interact with several proteins contributing to cancer cell migration and invasion via RAC1 activation." (PMID 39527598, 2024). "Here, we demonstrated that Trp320 of AXL is C-mannosylated, measured by mass spectrometry of recombinant AXL purified from various cancer cells." (PMID 39660536, 2024). "AXL’s biological role has been probed using a variety of strategies for cancer therapy, such as monoclonal antibodies or small chemical inhibitors that compete with ATP-binding enzymes." (PMID 38391974, 2024). "In this study, we developed AXL-specific sdAbs and evaluated their value for personalized cancer treatment." (PMID 38773967, 2024).
cancer (continued). "The interplay between the GAS6/AXL axis plays a fundamental role not only in the development of cancer but also in the physiological processes of cell differentiation and proliferation, survival, aggregation, and inflammation." (PMID 38391974, 2024). "Correspondingly, pathological activation of the AXL/GAS6 pathway in cancer represents the acquired resistance mechanism to chemo-, radio- or immune therapies." (PMID 38172210, 2024). "Current clinical trials focus on the combination of AXL inhibitors with chemotherapeutic agents and immunotherapies in cancer 8, 36-38." (PMID 38773967, 2024). "The role of AXL in cancer cells is broad, including invasion, drug resistance, and vasculogenic mimicry formation." (PMID 39660536, 2024). "When fused to an Fc-domain, sdAbs acquire additional therapeutic properties that can lead to a multidrug approach for the treatment of AXL-positive cancer patients." (PMID 38773967, 2024). "We also highlighted the potential of targeting the DDR pathway as an avenue for cancer treatment in AXL-overexpressing cancers." (PMID 37349576, 2023). "As expected, the majority of HN279 cancer cells expressed MDK, together with a number of genes associated with the pre-nodal phenotype (eg SNAI2, AXL, STAT2) that were unaffected by ICB." (PMID 36973261, 2023). "Another target, tyrosine receptor kinase AXL, has been found aberrantly activated in several cancer types and is also an essential EMT inducer." (PMID 36823234, 2023). "Here, we will specifically discuss the role AXL in promoting drug tolerance of cancer cells to treatment." (PMID 37328828, 2023). "The AXL positivity rate of the CellSearch® CTC‐AXL assay was defined as the ratio between the number of AXL+ cancer cells detected by the CellTracks analyzer and the initial 100 cancer cells." (PMID 38132919, 2023). "There is mounting evidence supporting AXL's role in the occurrence and progression of cancer, as well as drug resistance and treatment tolerance." (PMID 37328828, 2023). "The role of AXL in radiation responses and drug resistance makes it a potential therapeutic target for promoting anti-cancer treatment responses." (PMID 36980768, 2023). "Recently, substantial resources have been deployed to develop broad therapies targeting Gas6/AXL in cancer." (PMID 37265798, 2023). "Accumulating evidence supporting the role of AXL in inflammation, and cancer progression, metastasis, and treatment resistance, resulted in increased research attention on AXL inhibitors." (PMID 37047640, 2023). "AXL is a receptor tyrosine kinase expressed in different cancer cell types, and the gene expression is regulated by HIF1α and HIF2α in hypoxic cancer cells lacking VHL protein." (PMID 37190141, 2023). "With the expanding role of AXL to the development of cancer, AXL has been identified as a promising candidate for novel targeted chemotherapeutic agents." (PMID 37396176, 2023). "It was demonstrated that GAS6, which can bind to all three TAM receptors, is secreted by bone marrow stromal cells, especially osteoblasts, and induces dormancy in several cancer entities via AXL." (PMID 38203403, 2023). "This review aims to summarize the AXL's structure, the mechanisms regulating and activating it, and its expression pattern, especially in drug-resistant cancers." (PMID 37328828, 2023). "Consistent with its initial discovery as a transforming protein, inappropriate AXL expression (e.g., overexpression, ectopic expression) has been observed in a variety of common cancers." (PMID 37396176, 2023). "Currently, cancer drug development strategies targeting AXL and other family members of its receptor include small-molecule inhibitors, monoclonal antibodies, and soluble receptors." (PMID 37265798, 2023). "A better understanding of these mechanisms is crucial for the development of novel therapeutic strategies targeting AXL in cancer and other diseases." (PMID 37328828, 2023).
cancer (continued). "Multiple studies have demonstrated that AXL is involved in various signaling pathways that are critical for cancer initiation and progression." (PMID 37328828, 2023). "There is ample evidence supporting the important role of AXL in drug resistance across various types of cancers." (PMID 37328828, 2023). "AXL is also expressed in cancer cells and microenvironmental immune cells, including dendritic cells, macrophages, and NK cells." (PMID 36980534, 2023). "In recent years, AXL has emerged as a key player in various biological processes, including immune regulation, cellular signaling, and cancer progression." (PMID 37328828, 2023). "Anti-AXL chimeric antigen receptor (CAR)-T-cell therapy is a new precise targeted immunotherapy for cancer, which is currently under clinical trials (NCT05128786 and NCT03393936)." (PMID 37328828, 2023). "Multiple lines of evidence indicate that AXL is also involved in cancer progression and treatment tolerance." (PMID 37328828, 2023). "In human cancers, some of which overexpress AXL, GnRH receptor signaling is predominantly mediated by Gαi proteins." (PMID 37828510, 2023). "For the last selected gene set the associated predicted networks were mainly associated to cancer and in one of those emerged the TAM family of RTKs (TYRO3, AXL, MER) and in particular a slight AXL up-modulation in the gene expression." (PMID 37041632, 2023). "Overall, several evidence shows that AXL signaling plays a crucial role in different hallmarks of cancer as abnormal proliferation and survival, resistance to apoptosis, invasion and metastasis, angiogensis and immune suppression." (PMID 37143061, 2023). "Here, we show that the scaffold protein CNK2 promotes cancer cell migration by coupling the pro-metastatic receptor tyrosine kinase AXL to downstream activation of ARF6 GTPase." (PMID 37322019, 2023). "Single-cell RNAseq (scRNAseq) analysis of cancer-cell trajectories identifies a subpopulation of pre-metastatic cells, driven by actionable pathways including AXL and AURK." (PMID 36973261, 2023). "In this study we discovered a CNK2-dependent signalling axis triggered by the RTK AXL that promotes cancer cell migration, invasion, and metastasis." (PMID 37322019, 2023). "Many cancer cells, including chronic lymphocytic leukemia, breast and prostate carcinomas, and non-small cell lung cancers, show AXL-dependent PI3K/Akt signaling which drives proliferation, metastasis, invasion, and drug resistance." (PMID 37396176, 2023). "Upregulation of AXL expression is correlated with resistance to TKIs and chemotherapeutic agents in various types of cancer, including LUSC." (PMID 37291533, 2023). "AXL can contribute to drug tolerance, and its inhibition has been shown to reduce drug resistance in several types of cancer." (PMID 37328828, 2023). "AXL plays a major role in promoting resistance to several common chemotherapeutics and targeted anti-cancer therapies." (PMID 37469409, 2023). "Virtually all types of cancer treatment, such as chemotherapy, radiotherapy, and targeted therapy, can induce AXL expression, resulting in resistance to treatment." (PMID 36835239, 2023). "While the roles of MER and AXL in these cancer processes have been well described, less is known about the roles of TYRO3." (PMID 36454644, 2023). "This question remains to be answered in other cancer types where high phospho‐AXL levels are present." (PMID 36409270, 2023). "For example, AXL overexpression at the cancer cell surface correlates with decreased expression of the major histocompatibility complex 1 (MHC‐1) and increased expression of the immune checkpoint PD‐L1, leading to decreased CD8+ T‐cell antitumor activity." (PMID 38132919, 2023). "In NSCLC, AXL upregulation has been associated with EMT, with AXL being overexpressed in mesenchymal cancer cells compared to epithelial cancer cells." (PMID 36902280, 2023).